USP28 (ubiquitin specific peptidase 28)
Description:
Deubiquitinase involved in DNA damage response checkpoint and MYC proto-oncogene stability. Involved in DNA damage induced apoptosis by specifically deubiquitinating proteins of the DNA damage pathway such as CLSPN. Also involved in G2 DNA damage checkpoint, by deubiquitinating CLSPN, and preventing its degradation by the anaphase promoting complex/cyclosome (APC/C). In contrast, it does not deubiquitinate PLK1. Specifically deubiquitinates MYC in the nucleoplasm, leading to prevent MYC degradation by the proteasome: acts by specifically interacting with isoform 1 of FBXW7 (FBW7alpha) in the nucleoplasm and counteracting ubiquitination of MYC by the SCF(FBW7) complex. In contrast, it does not interact with isoform 4 of FBXW7 (FBW7gamma) in the nucleolus, allowing MYC degradation and explaining the selective MYC degradation in the nucleolus. Deubiquitinates ZNF304, hence preventing ZNF304 degradation by the proteasome and leading to the activated KRAS-mediated promoter hypermethylation and transcriptional silencing of tumor suppressor genes (TSGs) in a subset of colorectal cancers (CRC) cells.
Synonyms: KIAA1515
Tractability: Small molecule: a structure with a bound ligand is known; a high-quality ligand is known. PROTAC: UniProt records ubiquitination sites on it; ubiquitination databases record sites on it; its protein half-life has been measured; a small molecule that binds it is known.
Target class: Cysteine protease; Cysteine protease CA clan; Protease; Enzyme; Cysteine protease C19 family
Gene: Protein-coding gene on chromosome 11 (113,797,870 to 113,875,590, reverse strand). Ensembl gene ENSG00000048028.
Subcellular location: Nucleus, nucleoplasm
Subcellular location (Human Protein Atlas): Nucleoplasm; Nuclear bodies
Pathways (Reactome):
Metabolism of proteins: Ub-specific processing proteases
Gene Ontology:
Molecular function: cysteine-type deubiquitinase activity; deubiquitinase activity; protein binding
Biological process: cell population proliferation; cellular response to UV; DNA damage checkpoint signaling; DNA damage response; protein deubiquitination; protein deubiquitination involved in ubiquitin-dependent protein catabolic process; regulation of protein stability; response to ionizing radiation
Cellular component: nuclear body; nucleoplasm; protein-containing complex
Genetic constraint (gnomAD): Loss-of-function variants: 95 observed, 130.45 expected, observed/expected ratio (o/e) 0.73, 90% interval 0.62 to 0.86. The upper end of that interval is the gene's LOEUF score, 0.86, which puts it in group 3 of 6, group 1 being the genes least tolerant of losing a copy. Missense variants: 1,110 observed, 1,245.3 expected, observed/expected ratio (o/e) 0.89, 90% interval 0.85 to 0.94. Synonymous variants: 424 observed, 448.53 expected, observed/expected ratio (o/e) 0.95, 90% interval 0.87 to 1.02.
Homologues: Orthologues: chimpanzee USP28 (99% identical), macaque USP28 (99% identical), dog USP28 (95% identical), pig USP28 (94% identical), rat Usp28 (91% identical), rabbit USP28 (87% identical), guinea pig USP28 (84% identical), mouse Usp28 (83% identical), tropical clawed frog usp28 (62% identical), zebrafish usp28 (55% identical). Paralogues in human: USP25 (49% identical), USP24 (15% identical), USP9X (14% identical), USP9Y (13% identical), USP43 (12% identical), USP31 (12% identical), USP42 (11% identical), USP48 (11% identical), USP36 (11% identical), USP47 (11% identical), USP19 (10% identical), USP34 (10% identical), and 59 more.
Diseases named in the same sentence as USP28 in open-access papers:
USP28 is named in the same sentence as 71 diseases in open-access papers, as found by Europe PMC text mining. Sharing a sentence is not in itself a finding about the gene and the disease. The quoted sentences say what the papers report.
breast carcinoma (46 papers, 2013 to 2025). "In summary, BRCA1 mutated breast cancers were characterized by reduced cyclin E1 T62 phosphorylation and elevated USP28 expression." (PMID 34465787, 2021). "High serum epinephrine is associated with poor prognosis and activated LDHA/USP28/MYC/SLUG signaling axis in breast cancer patients." (PMID 30688660, 2019). "One study has revealed a critical mechanism underlying the epigenetic regulation by USP28 in breast cancer." (PMID 29415985, 2018). "Somatic mutations in the USP28 gene have been identified in lobular breast cancer cases." (PMID 32549302, 2020). "USP28 is a deubiquitinase that is found upregulated in solid tumors like colorectal cancer, squamous cell carcinoma and breast cancer." (PMID 40456839, 2025). "Elevated expression levels of USP28 are observed in colon and breast carcinomas, and the stabilization of c‐MYC by USP28 is critical for tumor cell proliferation." (PMID 40227962, 2025). "Transfer of miRNA-500a-5p from CAFs to cancer cells in breast cancer (BC) stimulates proliferation and metastasis through binding to ubiquitin-specific peptidase 28 (USP28)." (PMID 39935427, 2025). "In breast cancer, sEVs derived from CAFs that carry miR-500a-5p can enhance proliferation and metastasis by targeting ubiquitin-specific peptidase 28 (USP28)." (PMID 39684264, 2024). "In breast cancer, the interaction between Myc and deubiquitinases (USP28 and USP22) reinforces protein stability and contributes significantly to cell proliferation." (PMID 39146353, 2024). "A previous study revealed that chronic stress-induced epinephrine promoted the deubiquitylation of MYC by USP28 via lactate dehydrogenase A (LDHA)-dependent metabolic reprogramming in breast cancer." (PMID 38689092, 2024). "miR-500a-5p in CAF-derived EVs in breast cancer promotes proliferation and metastasis ability by targeting and reducing ubiquitin-specific peptidase 28 (USP28)." (PMID 36674900, 2023). "In breast cancer cell lines with USP28 knockdown or LSD1 knockdown, p21Cif1/Waf1 was upregulated, while SOX2 and Oct4 were downregulated." (PMID 36879346, 2023). "Specifically, the Y1117 of USP28 exhibited a higher phosphorylation level in breast cancer than in normal tissues." (PMID 37450415, 2023). "USP28 can deubiquitinate diverse substrates and then display two opposite roles in one kind of cancer, such as breast cancer." (PMID 36879346, 2023). "A large number of studies had shown that targeting USP28 would have potential therapeutic effects on a variety of cancers, including non-small cell lung cancer, breast cancer, colon cancer, glioma and bladder cancer." (PMID 35299740, 2022). "MiR-500a-5p transferred from CAFs-derived exosomes was shown to enhance breast cancer metastasis by binding to ubiquitin-specific peptidase 28 (USP28)." (PMID 35955480, 2022). "In accordance with these findings, our study revealed that USP28, as the target gene of miR-500a-5p, reversed the ability of miR-500a-5p to promoted breast cancer cell proliferation and metastasis, indicating that USP28 functions as a breast cancer suppressor." (PMID 33664871, 2021). "USP28, a therapeutic target for many tumors, promotes breast cancer growth in vivo through deubiquitination and stabilization of lysine-specific demethylase 1 (LSD1), which is essential in sustaining the pluripotency of embryonic stem cells." (PMID 34575114, 2021). "miR-500a-5p promotes proliferation and metastasis of breast cancer cells by binding to ubiquitin-specific peptidase 28 (USP28)." (PMID 34853307, 2021). "At the same time, histone deacetylase 5 (HDAC5) enhances USP28 stability and facilitates breast cancer cell proliferation in a LSD1-dependent manner." (PMID 34575114, 2021).
breast carcinoma (continued). "It is found that knockdown of USP28 induces differentiation and suppresses self-renewal in breast cancer stem cells (CSCs) by elevating expression of differentiation genes and decreasing expression of pluripotent molecules." (PMID 34575114, 2021). "We then detected the expression of EMT-related markers in breast cancer cells after upregulation and downregulation of USP28." (PMID 33664871, 2021). "Given the complexity of the various functions of USP28, specific mechanism for inhibiting breast cancer will be further studied in our future work." (PMID 33664871, 2021). "Given that our findings indicated that USP28 is regulated by miR-500a-5p, gain- and loss- of function experiments were conducted to determine the biological characteristics of USP28 in breast cancer cells." (PMID 33664871, 2021). "USP28 is highly expressed in many cancer types, such as in breast cancer, non-small-cell lung cancer (NSCLC), gastric cancer, bladder cancer, and colorectal cancer." (PMID 32549302, 2020). "In breast cancer, it has been shown that the deubiquitinase USP28 stabilizes LSD1 and regulates the self-renewal of breast CSCs (bCSCs) in vitro and tumor growth in vivo." (PMID 31627418, 2019). "In our study, vitamin C suppressed stress-induced LDHA, thus altering the lactate production to inhibit the USP28/MYC/SLUG axis in breast cancer stem cells." (PMID 30688660, 2019). "Analysis of possible targets for miR-29b-1-5p reveals that the top 4 targets, USP28, NEUROD1, LIN9 and WDR26 have all been previously associated with breast cancer." (PMID 30323900, 2018). "USP28 is a key regulator of the DNA damage checkpoint, high expression levels of USP28 are found in colon and breast carcinomas, and stabilization of MYC by USP28 is essential for tumour-cell proliferation." (PMID 24997798, 2014). "In addition, USP28 inhibition with AZ1 has already been found to be an effective therapeutic option in lung or breast cancer." (PMID 40456839, 2025). "That is, the role of USP28 in breast cancer is to suppress cancers." (PMID 36879346, 2023). "In breast cancer cell lines, a reduction in USP28 was observed following miR-500a-5p mimic transfection because miR-500a-5p could target USP28 at two potential binding sites in the 3’-UTR of USP28." (PMID 36879346, 2023). "In addition, CAF-derived EVs was discovered to transfer miR-500a-5p, by which ubiquitin-specific peptidase 28 (USP28) was directly targeted and blocked in breast cancer cells, thus promoting proliferation and metastasis of cancer cells." (PMID 35927755, 2022). "The miR-500A-5P of CAFS-Exos in BC patients can be transferred from adjacent CAFs to BCCs, and by binding to ubiquitin specific peptidase 28 (USP28), the miR-500A-5P of CAFs-Exos can considerably promote the proliferation and metastasis of breast cancer cells by giving it an aggressive phenotype." (PMID 36005690, 2022). "Moreover, USP28 also showed a trend towards reduced expression in breast cancer patients with lymph node metastasis." (PMID 33664871, 2021). "Furthermore, gene expression profiles of breast cancer from TCGA showed that the expression of USP28 had a downward trend in tumor tissues." (PMID 33664871, 2021). "Besides, the exosomal miR-500a-5p can promote breast cancer cell proliferation and metastasis by targeting and reducing the expression of ubiquitin-specific peptidase 28 (USP28)." (PMID 34852849, 2021). "Finally, USP28 has been targeted in several studies for the treatment of different cancers, such as non-small cell lung cancer, breast cancer, intestinal cancers, gliomas, and bladder cancer." (PMID 32927708, 2020). "Furthermore, the reduced expression of USP28, a gene known to affect onset and progression of liver and breast cancer, is likely to mediate glycogen-independent oncogenic functions." (PMID 32927708, 2020). "Also, high glucose consistently triggered HK2 and LDHA expression and stimulated the USP28/MYC axis in breast cancer cells." (PMID 30688660, 2019).
breast carcinoma (continued). "In a follow-up study, it was further confirmed that USP28 could modulate epigenetic events in breast cancer." (PMID 29415985, 2018). "High expression levels of USP28 have also been reported in colon and breast carcinoma, the deubiquitinating activity of USP28 is known to stabilize the levels of the oncogenic transcription factor Myc however the clinical implications of this are currently unclear." (PMID 24123619, 2013). "Hence, USP28 plays a significant role in inhibiting EMT in breast cancer." (PMID 36879346, 2023). "USP28 deletion is associated with 53.2%-9.7% of breast cancer cases, which reveals that USP28 gene deletion-mediated disruption of FBXW7 auto-ubiquitination might correlate with breast cancer development in certain way, but this remains to be further investigated." (PMID 37658431, 2023). "Also, USP28 is closely related to cell proliferation and metastasis in breast cancer." (PMID 37450415, 2023). "As a nucleoplasm-located DUB, USP28, ubiquitin-specific peptidase 28, is among the deubiquitinases that alter the stability and turnover of critical cancer oncoproteins such as cMYC involved in the proliferation and aggressiveness of colon and breast carcinoma and glioblastoma cells." (PMID 35884430, 2022). "Previous studies have revealed that expression of USP28 was strongly elevated in human colon and breast carcinomas, and overexpression of USP28 enhanced HIF-1α-dependent angiogenesis and promoted colorectal cancer, suggesting that it might play a critical role in tumor cellular pathways." (PMID 30622440, 2019). "Therefore, targeting USP28 may tune down the HDAC5/LSD1-mediated epigenetic process that drives breast cancer development and progression." (PMID 29415985, 2018). "For example, LSD1 is deubiquitinated and stabilized by USP28 and OTUD7B to support breast cancer stemness and metastasis." (PMID 39563370, 2024). "High expression of USP28 and MAST1 was observed in lung cancer, breast cancer and colon cancer samples." (PMID 38498222, 2024). "Non-parametric spearmen correlation revealed a positive correlation between USP28 and MAST1 expression in lung cancer (Spearman’s rho = 0.81); breast cancer (Spearman’s rho = 0.61) and colon cancer (Spearman’s rho = 0.76)." (PMID 38498222, 2024). "USP22 and USP36 regulate the cellular turnover of c-MYC in breast cancer, and c-MYC expression is stabilized by USP28 and USP37 in colon carcinoma and lung cancer, respectively." (PMID 39664521, 2024). "The deubiquitinase ubiquitin specific peptidase 28 (USP28) can stabilize LSD1 to promote stemness and drug resistance in breast cancer cells." (PMID 36632469, 2023). "It was demonstrated that elevated lactate production through induced LDHA activity directs USP28-mediated deubiquitination and the stabilization of MYC, thereby promoting stem-like traits in breast cancer." (PMID 36230479, 2022). "For example, USP28 has been reported to stabilize MYC and to be highly expressed in colon and breast cancers." (PMID 34272356, 2021). "Collectively, our data suggested that high levels of miR-500a-5p in CAFs are transferred into tumor cells and downregulates USP28 expression, which promotes cell proliferation, metastasis and EMT in breast cancer." (PMID 33664871, 2021). "However, the underlying mechanisms of breast cancer suppression by USP28 are not clear." (PMID 33664871, 2021). "The adjusted pH is conducive to the ubiquitin-specific protease 28 (USP28)-mediated ubiquitination and stabilization of MYC, and MYUG activates the SLUG promoter, which promotes the development of stem-like traits in breast cancer." (PMID 32974180, 2020). "All breast cancer tissues displayed higher LDHA and USP28 protein levels when compared with adjacent normal tissues." (PMID 30688660, 2019). "This leads to a switch to lactate production, and the adjusted pH then directs USP28-mediated deubiquitination and stabilization of MYC, thereby promoting stem-like traits in breast cancer." (PMID 30688660, 2019).
breast carcinoma (continued). "Ubiquitin-specific peptidase 28 (USP28) plays a role in the stabilization of KDM1A in multiple cancers, including breast cancer, through its de-ubiquitination." (PMID 29921310, 2018). "In immunodeficient mouse model with breast cancer, chronic stress-induced epinephrine activates key enzyme LDHA to produce lactic acid, forming an acidic microenvironment to facilitate USP28-mediated deubiquitination of MYC, resulting in enhanced cancer stemness." (PMID 39054537, 2024). "One study found that USP28 could affect the cell cycle and proliferation by regulating MYC abundance in colon and breast carcinomas." (PMID 37450415, 2023). "Both LSD1 and histone deacetylases (HDACs) facilitate breast cancer proliferation, and interestingly, HDAC5 could promote the stability of USP28." (PMID 29415985, 2018). "We further review the studies where USP28 was targeted for treating multiples cancers including non-small cell lung cancer, breast cancer, intestinal cancers, gliomas, and bladder cancer." (PMID 29415985, 2018). "Notably, it has been shown that CAFs secrete exosome miR-500a-5p, which could bind to ubiquitin-specific peptidase 28 (USP28), thereby facilitating progression and metastasis in both the basal breast cancer cell line MDA-MB-231 and the luminal cell line MCF7." (PMID 38001753, 2023). "In addition, HDAC5 promoted breast cancer development and progression in a LSD1-dependent manner 42, however, there were no direct evidence that USP28 was involved in breast cancer progression in the study." (PMID 33664871, 2021). "In contrast, the hypoxia-mediated USP28 decrease could not be observed in either MDA-MB-231 breast cancer cells or in mouse embryonic fibroblasts." (PMID 31208103, 2019). "However, as the search showed, the higher level of USP28 still has nonnegligible value in predicting better survival and TNM classification of breast cancer." (PMID 36879346, 2023). "A previous study demonstrated that although knockdown of USP28 contributes to the increase in E-cadherin and promotion of gastric cancer invasion, accumulation of α-SMA and reduction of E-cadherin appeared in breast cancer cell lines without USP28." (PMID 36879346, 2023).